RN7SL120P (RNA, 7SL, cytoplasmic 120, pseudogene)
Gene: Miscellaneous RNA gene on chromosome 3 (1,065,580 to 1,065,875, reverse strand). Ensembl gene ENSG00000244169.
Homologues: Orthologues: chimpanzee Metazoa_SRP (98% identical), macaque Metazoa_SRP (94% identical), dog Metazoa_SRP (67% identical). Paralogues in human: RN7SL1 (78% identical), RN7SL2 (78% identical), RN7SL828P (78% identical), RN7SL3 (77% identical), RN7SL708P (77% identical), RN7SL301P (77% identical), RN7SL493P (77% identical), RN7SL769P (77% identical), RN7SL220P (76% identical), RN7SL444P (76% identical), RN7SL218P (76% identical), RN7SL336P (76% identical), and 703 more.